MMP1 (matrix metallopeptidase 1)
Diseases named in the same sentence as MMP1 in open-access papers (continued):
Sharing a sentence is not in itself a finding about the gene and the disease.
hepatocellular carcinoma (continued). "For example, MMP1 overexpression can promote EMT through ECM degradation, leading to the enhanced invasion and migration of hepatocellular carcinoma (HCC) cells." (PMID 36408277, 2022). "CircDLC1, a prognostic marker of hepatocellular carcinoma (HCC), inhibits the motility of HCC by sequestering HuR from matrix metalloproteinase-1 (MMP1) mRNA." (PMID 36224588, 2022). "In hepatocellular carcinoma (HCC), upregulation of the EMT-TF Snail not only repressed E-cadherin transcription but also increased expression of MMP-1, MMP-2, MMP-7, and MT1-MMP leading to accelerated invasion." (PMID 31540068, 2019). "The incubation of MSCs with conditioned medium of hepatoma cell culture was found to increase MSC migration by significantly increased levels of MIP-1δ, MIP-3α, and MMP-1, suggesting the dependency of MSC migration on MMP-1." (PMID 27612636, 2016). "Furthermore, due to overexpression of BATF3 in hepatocellular carcinoma cells, JUN and BATF3 interact at the matrix metalloproteinase-1 (MMP-1) promoter element, resulting in repression of MMP-1 transcription." (PMID 29662618, 2018). "The mRNA levels of both MMP-2 and MMP-14 in human hepatocellular carcinoma (HCC) cell SMMC-7721 were up-regulated by Cu2+ in a concentration dependent manner, whereas the mRNA levels for other tested MMPs (MMP-1, MMP-3 and MMP-9) were not changed when treated with up to 40 μM Cu2+." (PMID 28881637, 2017).
glioma (32 papers, 2009 to 2025). A benign or malignant brain and spinal cord tumor that arises from glial cells (astrocytes, oligodendrocytes, ependymal cells). "Elevated MMP-1 expression is a hallmark of highly malignant gliomas and is implicated in enhancing tumor invasiveness and malignancy." (PMID 39007144, 2024). "Notably, MMP-2 and MMP-9 have been associated with glioma invasiveness, while other MMPs, such as MMP-1 and MMP-7, are linked to metastatic gliomas." (PMID 40265458, 2025). "While much research has focused on MMP-1’s downstream mechanisms in gliomas, its upstream regulators remain underexplored, which is crucial for understanding glioma invasiveness." (PMID 39007144, 2024). "Our study not only confirms the upregulation of MMP-1 in high-grade gliomas but also identifies AGBL4 as a novel upstream regulator of MMP-1." (PMID 39007144, 2024). "We subsequently found that ADAMTS20 and FREM3 were interrelated lower risk of glioma using Cox regression analysis, whereas LAMB4, MMP1, and MMP7 showed high risk of glioma." (PMID 37335645, 2023). "This study demonstrated that high-risk genes (LAMB4, MMP1, MMP7) promote glioma progression and negatively correlate with patient prognosis." (PMID 37335645, 2023). "The top most affected genes included GAP43 which has recently been shown to play a key role in glioma invasiveness through tumor microtube formation and MMP1 which facilitates tumor microtubes' infiltration throughout the brain." (PMID 37689115, 2023). "Among the five core target genes, MMP-1 is considered closely related to the malignant degree of glioma and the prognosis of glioma patients." (PMID 37759283, 2023). "Specifically, a specific subgroup of MMPs (including MMP-1, -2, -7, -9, -11, -12, -14, -15, and -25) was shown to be strictly related to glioma grading and glioblastoma development." (PMID 36980765, 2023). "MMP-1 protein level is increased with the tumor grade and correlated with increased glioma invasiveness." (PMID 33809462, 2021). "It was previously reported that the MMP-1 protein level increases with the tumor grade and is related to increased glioma invasiveness." (PMID 27043542, 2016). "Since MMP-1 levels correlate well with tumor grade and glioma invasiveness, flow-induced attenuation in MMP-1 expression implies a diminished invasive potential for U87 gliomas." (PMID 21637818, 2011). "MSCs expressing low levels of MMP1 fail to response to signaling cues from human glioma cells even though other MMPs are present at levels similar to the highly migrating MSCs." (PMID 19489099, 2009). "Taken together, our results showed, for the first time, the functional importance of the MMP1/PAR1 axis in modulating the migration of MSCs toward human glioma." (PMID 19489099, 2009). "In conclusion, we report that the migratory activity of MSCs toward glioma is mediated via the MMP1/PAR1 axis in vitro and in vivo." (PMID 19489099, 2009). "Our results highlighted the critical role that MMP1 plays in the process of mobilizing MSCs toward human glioma cells." (PMID 19489099, 2009). "The role of MMP1 in the migration of MSC-1 toward human glioma was further investigated using Varani migration assay." (PMID 19489099, 2009). "Ectopic expression of MMP1 in these poorly migrating cells also rendered the cells responsive to the signaling cues from the glioma cells in vivo." (PMID 19489099, 2009). "Functional inactivation of MMP1 abrogated the migratory potential of MSCs toward glioma-conditioned medium." (PMID 19489099, 2009). "Additionally, TLR2 activation can upregulate MMP1 expression in microglia and gliomas, promoting tumor growth and migration." (PMID 39458936, 2024). "Inhibition of MMP1 expression can significantly inhibit glioma proliferation and invasion." (PMID 37759283, 2023). "Other indicators of EMT activation in glioma NS include MMP1, TIMP1 and PLOD2." (PMID 36231068, 2022). "Meanwhile, MMP1 has been shown to be necessary for the migration of BM-MSCs toward gliomas." (PMID 32899628, 2020).
glioma (continued). "Glioma lethality was rescued by MMP1 or MMP2 down regulation." (PMID 31846454, 2019). "Similarly, our study finds that SNHG20 is highly expressed in glioma tissues and cells, and knockdown of SNHG20 reduces VM of glioma by reducing the expression of VM-related molecular MMP1, MMP9, VE-Cadherin." (PMID 30744670, 2019). "Next, we explored whether the accumulation of MMPs in glioma was due to a transcriptional up-regulation of MMP1 and MMP2." (PMID 31846454, 2019). "Therefore, the data suggest that C2 ceramide is a broad spectrum inhibitor of MMP-1, -3, and -9 that plays a crucial role in glioma invasion." (PMID 27043542, 2016). "The migration of transplanted stem cells through the brain parenchyma may also be aided by their secretion of matrix metalloproteases (MMPs), because BMSCs require MMP1 to migrate toward human gliomas." (PMID 20550687, 2010). "Thus, using a C6 glioma cell culture model and molecular docking, we suggest that the modulation of metalloproteinase 1 (MMP1), via a lectin glycan interaction, may take part in the glioma cell death mechanism triggered by ConGF." (PMID 36296679, 2022). "Similarly, GASC exosomes were enriched in miR-451 and miR-150, which are known to inhibit GSC growth and glioma cell proliferation, invasion and apoptosis through the Akt pathway and to suppress glioma cell proliferation and migration by targeting MMP1, respectively." (PMID 33287106, 2020). "GBP1 is important for EGFR-mediated matrix metalloproteinase 1 (MMP1) expression and glioma cell invasion in vitro, establishing it as a potential therapeutic target for inhibiting GBM invasion." (PMID 38893192, 2024). "For the sake of clarifying the expression of BMGs in glioma, this study screened 9 BMGs that were upregulated in glioma (FBN2, FREM3, Lamb4, MEP1A, MMP1, MMP7, OPTC, EVA1A, and ADAMTS20) from TCGA -GTEX expression matrix." (PMID 37335645, 2023). "To investigate the expression of the MMP family in glioma development, we investigated the mRNA expression levels of the nine MMP family members (MMP1–29) in The Cancer Genome Atlas (TCGA) and GETx database." (PMID 35350840, 2022). "FOXK1 inhibits transcription by binding to the promoters of MMP1, MMP9 and VE-Cadherin and inhibits vasculogenic mimicry formation of glioma cells." (PMID 30744670, 2019). "FOXK1 down-regulates the levels of VM-related molecular MMP1, MMP9, VE-Cadherin by binding to their promoters and inhibited the VM formation in glioma cells." (PMID 30744670, 2019). "This study demonstrated that the ZRANB2/SNHG20/FOXK1 axis played an important role in regulating the expression of VM-related molecules MMP1, MMP9 and VE-Cadherin, and regulated the VM formation of glioma." (PMID 30744670, 2019). "To determine this, we used the transcriptional reporters MMP1-lacZ and MMP2-lacZ in control and glioma, and the results show only a few cells with MMP1 and MMP2 transcriptional reporters activated in glial cells (arrowheads) in both control and glioma brains." (PMID 31846454, 2019). "FOXK1 significantly reduces VM-related molecules MMP1, MMP9 and VE-Cadherin and reduced VM in glioma cells." (PMID 30744670, 2019). "FOXK1 inhibited transcription by binding to the promoters of MMP1, MMP9 and VE-Cadherin and inhibited the proliferation and migration, invasion and VM formation of glioma cells." (PMID 30744670, 2019). "Co-transfection of SNHG20(−) cells with FOXK1(+) strongly decreased the expression of MMP1, MMP9, VE-Cadherin and strongly inhibited the abilities of proliferation, migration, invasion and VM of glioma cells." (PMID 30744670, 2019). "The induction of GBP1 is essential for EGFR-mediated matrix metallopeptidase-1 (MMP1) expression and glioma cell invasion in vitro and in vivo." (PMID 26848767, 2016). "Matrix Metalloproteinase (MMP) inhibition experiments and assays demonstrated that the glioma cells depended on MMP activity to invade, and suppression in motility correlated with downregulation of MMP-1 and MMP-2 levels." (PMID 21637818, 2011).
glioma (continued). "Matrix metalloproteinase 1 (MMP1) is involved in the process of MSC migration, as both knockdown of MMP1 RNA and blockage of its cognate receptor PAR1 significantly reduced migration towards glioma-conditioned medium." (PMID 38396962, 2024). "Additionally, increased MMP-1 and PAR1 expression correlates with higher histological malignancy and poorer clinical outcomes in gliomas." (PMID 39007144, 2024). "So-Young Kim and colleagues discovered that curcumin potently inhibited glioma invasion by inhibiting all the MAPK pathways (JNK, p38, ERK), which then suppressed phorbol myristate acetate (PMA)-induced mRNA expression of MMP-1, -3, -9, and -14 in U87MG and U373MG cells." (PMID 33809462, 2021). "Co-transfection of ZRANB2(−) cells with SNHG20(−) could strongly decrease the expression of MMP1, MMP9, VE-Cadherin and strongly inhibit the abilities of proliferation, migration, invasion and VM of glioma cells." (PMID 30744670, 2019). "To corroborate these results, we undertook qPCRs experiments with RNA extracted from control and glioma larvae, which revealed no change in the transcription (mRNA levels) of MMP1 or MMP2 in glioma samples relative to the control." (PMID 31846454, 2019). "To investigate whether PAR1 plays a role in MMP1-dependent chemotaxis of MSCs, we examined whether the inhibition of PAR1 proteolysis may affect the ability of MSC-1 to migrate toward glioma-CM." (PMID 19489099, 2009). "For example, bioinformatics analyses have shown that certain MMPs, such as MMP-1, MMP-11, MMP-19, and MMP-21, are consistently upregulated in GBM compared to normal brain tissue, suggesting that they may serve as biomarkers for diagnosis and prognosis in high-grade gliomas." (PMID 40265458, 2025). "There has been no report whether FOXK1 regulates transcription of MMP1, MMP9 and VE-Cadherin and regulates the VM formation in glioma." (PMID 30744670, 2019).
lymph node metastasis (32 papers, 1998 to 2024). "This correlates with reports of the importance of MMP-1 in OAC in the literature as a strong association between high MMP-1 expression and positive lymph node metastases has been shown." (PMID 33126685, 2020). "Furthermore, we found that MMP-1.3 polymorphism contributed to the susceptibility of lymph node metastasis." (PMID 24505369, 2014). "Our findings of high MMP-1 expression being associated with lymph node metastases in patients with EAC indicate that MMP-1 expression may be involved in promotion of cancer progression in addition to other clinicopathological characteristics." (PMID 20946664, 2010). "The MMP-1 expression was significantly higher in CRC cases at stage IV and the up-regulation of MMP-1 was found in cases with lymph node metastasis as well as distant metastasis." (PMID 35456495, 2022). "Some studies have confirmed that the upregulation of MMP1 is related to lymph node metastasis in NPC." (PMID 36555343, 2022). "Overexpression levels of MMP-1 and CTGF were associated with lymph node metastasis, distant metastasis, tumour histopathological grading, advanced stage, and poor survival (p < 0.05)." (PMID 35456495, 2022). "High expression levels of MMP-1 positively corrected with lymph node metastasis and advanced tumor, node, metastasis stage." (PMID 34741018, 2021). "MMP1 was correlated with lymph node metastasis and indicated unfavourable survival in cervical cancer." (PMID 32300605, 2020). "MMP1 expression was a better predictor factor of lymph node metastasis than well established pathological parameters (AUC: MMP1 = 0.751; histological grade = 0.672; perineural invasion = 0.596; tumor size = 0.376)." (PMID 28122331, 2017). "Among these genes, increased expression of MMP1 was observed in cases with lymph node metastasis, further confirmed by RT-qPCR in the validation set of samples." (PMID 28122331, 2017). "We also analyzed the relationship between MMP1 protein expression, tumor size, lymph node metastasis, differential grade, and ER, PR, HER2 status." (PMID 29207651, 2017). "Although hsa-miR-145 down-expression was unable to predict poor prognosis in our cohort of cases, its target MMP1 showed increased expression levels in patients with lymph node metastasis." (PMID 28122331, 2017). "MMP1 gene expression levels were a better predictor of lymph node metastasis than tumor size, histological grade and perineural invasion." (PMID 28122331, 2017). "Higher MMP1 expression was detected as a better predictor of lymph node metastasis than the clinical-pathological data." (PMID 28122331, 2017). "In the present study, MMP1 showed superior performance in discriminate lymph node metastasis in PeCa compared with established clinical-pathological parameters." (PMID 28122331, 2017). "MMP1 overexpression was also correlated with peritoneal metastasis and lymph node metastasis of GCs." (PMID 26701885, 2016). "MMP-1 expression in EC cells is associated with poor prognosis; MMP-2 and MMP-3 expression is positively correlated with depth of invasion, lymph node metastasis, and vessel permeation." (PMID 26916665, 2016). "Specifically, in CRC, the aberrant activation of MMP-1 correlates with advanced stage, lymph node metastasis and poor prognosis." (PMID 26461477, 2015). "Analyses of clinical specimens revealed that expression of MMP1 correlated with lymphatic invasion and lymph node metastasis." (PMID 24063540, 2013). "In SCC and lymph node metastasis, a detectable immunostaining for MMP-1 in stromal cells and in some carcinoma cells was observed." (PMID 9649139, 1998). "In oral SCC and lymph node metastasis, MMP-1 mRNA was detected in fibroblastic cells of tumoral stroma." (PMID 9649139, 1998). "Additionally, upregulation of MMP-1 has been demonstrated to be correlated with lymph node metastasis in some cancers, such as nasopharyngeal carcinoma (NPC)." (PMID 34078895, 2021).
lymph node metastasis (continued). "Additionally, salivary MMP-1 levels in oral cavity cancer patients were highly correlated with tumor progression (tumor size, lymph node metastasis, and overall stage)." (PMID 32823758, 2020). "In the present study, we suggest that salivary MMP-1 is a good biomarker for (i) early-stage OSCC screening of high-risk populations; (ii) monitoring OSCC progression or disease recurrence; (iii) monitoring the status of neck lymph node metastasis in OSCC." (PMID 32823758, 2020). "Furthermore, MMP1 expression level was a predictive marker for lymph node metastasis in patients with PeCa." (PMID 28122331, 2017). "In 2004, Matsumura and his coworkers firstly examined the contribution of MMP1 genotypes to GC risk, but findings that the genotypes were neither associated with the GC risk nor the prognosis such as lymph node metastasis and clinical stages." (PMID 28612708, 2017). "MMP-1.4 polymorphism with a combination of the TC and CC genotype shows a negative correlation for regional lymph node metastasis in addition to distant metastasis, contradicting MMP-1.3 polymorphism." (PMID 24505369, 2014). "High MMP-1 levels were associated with lymph node metastases but not with poorer survival (p = 0.307)." (PMID 20946664, 2010). "Furthermore, MMP1 is a predictive marker of lymph node metastasis in PeCa." (PMID 28122331, 2017). "Recently, MMP-1 was reported to be remarkably expressed in NPC-BM1 biopsies and the up-regulation of MMP-1 has been demonstrated to be correlated with lymph node metastasis of NPC-BM1." (PMID 28672814, 2017). "MMP-1 expression was significantly higher in BC patients with axillary lymph node metastasis than without lymph node metastasis and was the highest in TNBC tissues compared to those in HR+ and HER2+ BC tissues." (PMID 34771423, 2021). "Positive H. pylori infection and positive expression of MMP-1 and MMP-10 were associated with lymph node metastasis and clinical stage (P<0.05), but not with age, gender or differentiation degree (P>0.05)." (PMID 25120597, 2014).